S100A8 (S100 calcium binding protein A8)
Diseases named in the same sentence as S100A8 in open-access papers (continued):
Sharing a sentence is not in itself a finding about the gene and the disease.
Sepsis (continued). "Consequently, the pretreatment of S100a9-knockout mice with the S100A8/A9 heterodimer or the more potent S100A8 homodimer directly after birth rescued murine neonates from fatal courses of later sepsis." (PMID 32425933, 2020). "Withdrawal or blocking of S100A8/A9 terminated the activation of the MyD88-dependent gene program and came along with an increased inflammatory response toward microbial stimuli in vitro and in vivo in experimental sepsis models." (PMID 32425933, 2020). "S100A8/A9 levels were elevated in eight neonates with confirmed sepsis." (PMID 30555806, 2018). "First, we tested whether S100A8/A9 proteins accumulate inplasma obtained from sham and septic mice during early and late sepsis." (PMID 29204146, 2017). "To determine whether S100A8/A9 expression insepsis patients correlates with sepsis inflammation, we first measured plasmaS100A8/A9 during human sepsis." (PMID 29204146, 2017). "However, we showed that S100A8/A9 proteins in septic mice decreased in thelate sepsis phase, despite elevated levels of mRNAs and proteins in circulatingphagocytes and Gr1+CD11b+ MDSCs in the bone marrowand spleens." (PMID 29204146, 2017). "Overwhelming release of S100A8/A9 could be detrimental for the host during sepsis contributing to ongoing inflammation, organ damage and/or exhaustion of the immune system." (PMID 25860480, 2015). "Patients with severe sepsis have an increased serum S100A8/A9 concentration." (PMID 24956170, 2014). "As S100 proteins have been defined as clinical markers of inflammation in a previous study, S100a8 and S100a9 levels in the lymph may be a marker for the diagnosis of early stage sepsis." (PMID 25242054, 2014). "In abdominal sepsis patients, the S100a8/S100a9 levels in the abdominal fluid were >15-fold that in the plasma, indicating that S100a8/S100a9 expression was induced primarily at the site of infection during sepsis." (PMID 25242054, 2014). "Studies in mice indicate that S100A8/9 might contribute to cardiovascular dysfunction resulting from sepsis and atherosclerosis." (PMID 23209553, 2012). "Among them, the neutrophil microbicidal peptides alpha defensins and the highly pro-inflammatory calgranulins proteins S100A8/A9 and S100A12 are now considered putative pathogenic factors in sepsis, cardiovascular diseases, rheumatoid arthritis or atherosclerosis." (PMID 20652028, 2010). "Additionally, resistin was significantly correlated with S100A8/A9, suggesting that the combination of these biomarkers could be useful for immune typing of sepsis patients." (PMID 40568710, 2025). "As highlighted, S100A8/A9 and resistin enhances the ability to distinguish sepsis patients from healthy individuals, assess the severity of sepsis, identify the infecting bacterial type, perform immunotyping of sepsis patients, and predict patient survival outcomes." (PMID 40568710, 2025). "Moreover, S100A8/A9 showed the potential as a biomarker for sepsis diagnosis." (PMID 37978525, 2023). "However, the functional role of S100A8/A9 in sepsis-induced acute liver injury (ALI) and whether it exerts a therapeutic effect on this disease remain elusive." (PMID 36768433, 2023). "However, the role of S100A8/A9 in the regulation of sepsis-induced ALI remains known." (PMID 36768433, 2023). "Therefore, blocking the increase of S100A8/A9 may break this vicious cycle and provide a new molecular target for improving vascular hyperpermeability in sepsis." (PMID 37978525, 2023). "Moreover, identifying this period as a critical phase in which the regulation of inflammatory responsiveness shifts from S100A8/A9-programming to an adult-like endogenous regulation allowed understanding why the incidence of late-onset sepsis is highest in the first 2 weeks of life." (PMID 32425933, 2020).
Sepsis (continued). "Oxidized S100A8 is a known inhibitor of mast cell degranulation and FcεR-crosslinking-induced cytokine secretion, and at least two studies indicate that it has an anti-inflammatory role in acute asthma and sepsis, which is attributed to inhibition of inflammatory pathways mediated by ROS." (PMID 31437241, 2019). "Therefore, S100A8/A9 proteins and/or mRNA expression may be regulated in accordance with the development of immune dysfunctions in sepsis." (PMID 24956170, 2014). "This could be related with clinical observations including our own that show a link between increased S100A8/A9 levels after sepsis and an increased risk of death or nosocomial infections." (PMID 24956170, 2014). "A study revealed that S100A8/A9 inhibitor attenuates the binding of S100A8/A9 to TLR4, alleviates the inflammatory response to sepsis-induced AKI, and protects the kidney." (PMID 40709185, 2025). "These pathways’ convergence emphasizes how crucial S100A8 and S100A9 are in coordinating the inflammatory response during sepsis." (PMID 41303672, 2025). "Among sepsis patients admitted to the ICU, the AUC for S100A8/A9 in predicting 28-day mortality was 0.617 (P = 0.032; 95% confidence bounds 0.513–0.721), and for SOFA was 0.750 (P < 0.0001; 95% confidence bounds 0.660–0.840)." (PMID 40568710, 2025). "Members of the S100 protein family, S100A8, S100A9 and S100A6 are essential to the pathophysiology of sepsis." (PMID 41303672, 2025). "During sepsis, the bone marrow releases a large amount of immature granulocyte (IGs) through emergency granulopoiesis, such as CEACAM8+Neu, S100A8/9hiNeu, IL1R2+Neu, PADI4+Neu, MPO+Neu and cycling MK167+CYP1B1+Neu." (PMID 40356926, 2025). "Elevated levels of S100A8 and S100A12 are considered a potential biomarker of sepsis in human patients, and their levels of expression have been associated with poor disease outcomes." (PMID 40599378, 2025). "At the protein level, the proteins S100A8 and SERPINA10 were found to be biomarkers for severe burn patients with sepsis, and the results of scRNA-seq also revealed the important role of neutrophils in the early stages of severe burn injuries." (PMID 36659877, 2023). "First, the effect of S100A8/A9 on septic AKI needs to be clarified in S100A9 knockout mice and other animal models of sepsis." (PMID 37547329, 2023). "The S100A8/A9, occludin, and VE-cadherin protein expression levels in the lungs of CLP-induced mice with sepsis were measured to explore the functional role of S100A8/A9 in pulmonary vascular hyperpermeability in sepsis." (PMID 37978525, 2023). "Examples of genes related to this pathway that were differentially expressed in our sepsis samples include DEFA1, DEFA3, S100A8, S100A9 and RNASE6." (PMID 37731199, 2023). "Additionally, our findings suggest that S100A8/A9 could serve as a biomarker for sepsis diagnosis." (PMID 37978525, 2023). "The concentrations of the proteins S100A8, MMP8, CSF3, and IL-6, were measured in peripheral blood samples from 31 sepsis patients to validate the critical extracellular proteins identified in the study." (PMID 37901226, 2023). "Since S100A8/A9 represents an endogenous ligand of TLR4, it has been manifested to mediate inflammatory cascades during sepsis." (PMID 37337301, 2023). "To our knowledge, we are the first to report a link between elevated S100A8/A9 levels and SIMD development in severe sepsis patients requiring ICU care." (PMID 37773186, 2023). "In comparison to the sham-operated group, sepsis rats had higher levels of MMP8 and S100A8 proteins in their venous blood (both p<0.05) and cerebrospinal fluid (p=0.0506, p<0.0001, respectively)." (PMID 37901226, 2023). "We provide evidence for a connection between high plasma S100A8/A9 and LV dysfunction at ICU admission in patients with severe sepsis." (PMID 37773186, 2023).
Sepsis (continued). "Patients with systemic onset juvenile idiopathic arthritis and Still’s disease are estimated to have up to 20-fold lower blood levels of S100A8/A9 than FMF, whereas patients with sepsis or cryopyrinopathies have up to 200-fold lower blood levels." (PMID 38250061, 2023). "Our qPCR results and ROC curve analyses confirmed the accuracy of S100A8, S100A9, and CR1 in diagnosing sepsis as well as in predicting in-hospital mortality among patients with sepsis." (PMID 37298316, 2023). "Specifically, the expression levels of these 4 genes were increased > 4.0-fold in patients with sepsis compared with those in healthy subjects: ANXA3 (28.1-fold), S100A8 (4.9-fold), S100A9 (4.4-fold), and MMP9 (69.2-fold)." (PMID 32922168, 2020). "Narciclasine effectively suppressed the S100A8 and S100A9 protein expression in the livers of neonatal septic rats compared to the untreated sepsis group." (PMID 32076015, 2020). "This shows the potential influence and effect of the S100A8, S100A9 proteins in conditions like sepsis and shock and the need to neutralize its deleterious effects." (PMID 32076015, 2020). "Further qRT-PCR validation indicated that four genes are differentially expressed between patients with sepsis and healthy subjects (MMP9, S100A8, S100A9, and ANXA3)." (PMID 32922168, 2020). "Narciclasine treatment showed significant reduction of S100A8 and S100A9 levels in the lung and liver homogenates compared to the untreated sepsis group." (PMID 32076015, 2020). "We also found that narciclasine effectively reduced the S100A8 and S100A9 mRNA expression in the livers when compared to the untreated sepsis group." (PMID 32076015, 2020). "S100A8 and S100A12 in amniotic fluid from pregnant women were found to be the strongest predictor of increased early-onset sepsis incidence in neonates of pregnant women." (PMID 29942307, 2018). "That this new paradigm maytranslate to human sepsis, we show that S100A8/A9 intracellular mRNA and protein levelsin phagocytes are elevated in patients with more chronic sepsis, and that a correlationmay exist between this repressor like phenotype and human sepsis mortality." (PMID 29204146, 2017). "Because S100A8 protein is diminished in theS100A9 knockout mice, we examinedwhether reconstitution of the S100A9 knockout mice with S100A8 and/or S100A9 affectslate sepsis responses." (PMID 29204146, 2017). "In the current study, we thus evaluated the regulation of S100A8 and S100A9 mRNA expressions in an ex vivo model of sepsis-induced immune dysfunctions (endotoxin tolerance)." (PMID 24956170, 2014). "Another notable pathway expressed at higher levels in sepsis survivors related to the receptor for advanced glycation endproducts (RAGE) pathway and included the RAGE-related genes S100A8, S100A9, S100A12, and formyl peptide receptor 1 (FPR1)." (PMID 25538794, 2014). "The serum levels of S100A8/A9 in non-shock sepsis patients were also markedly higher than those in healthy individuals (P < 0.05)." (PMID 40568710, 2025). "Serum S100A8/A9 concentrations in surviving sepsis patients were significantly higher than in non-surviving patients." (PMID 40568710, 2025). "Herein, we established a SiH‐based nanosponge (denoted as SiH/ABR@PLGA) for in situ sustainable hydrogen release, and further cooperated with an alarmin protein S100A8/A9 inhibitor, ABR2575 (ABR) for synergistic anti‐inflammation therapy toward sepsis‐induced ALI." (PMID 39737874, 2025). "The median S100A8/A9 concentration at admission was 368.5 ng/mL (252.6-679.4 ng/mL) in sepsis patients, 356.8 ng/mL (216.1-503.9 ng/mL) in non-septic ICU patients, and 265.0 ng/mL (157.3-401.2 ng/mL) in healthy controls." (PMID 40568710, 2025). "First, serum S100A8/A9 levels were markedly elevated in sepsis patients relative to non-sepsis patients and healthy individuals, making it a potential diagnostic marker for sepsis." (PMID 40568710, 2025).
Sepsis (continued). "And nonsurvivors with sepsis without shock demonstrated significantly elevated serum S100A8/A9 levels (P < 0.001), whereas resistin levels remained comparable between septic shock and non-shock sepsis nonsurvivors (P = 0.38)." (PMID 40568710, 2025). "In the validation cohort, S100A8/A9 concentrations were substantially raised in sepsis patients in comparison with healthy individuals and non-sepsis patients (P < 0.05)." (PMID 40568710, 2025). "Additionally, this study demonstrated significant correlations between resistin, S100A8/A9, CRP, and IL-6 in sepsis patients." (PMID 40568710, 2025). "The most likely explanation for this finding is that the majority of non-surviving sepsis patients in this study were in an immunosuppressive state, with compromised immune function, leading to decreased production and release of S100A8/A9." (PMID 40568710, 2025). "While serum S100A8/A9 levels were higher in sepsis patients compared to non-sepsis patients and healthy individuals, severe sepsis cases, including non-survivors, exhibited lower S100A8/A9 expression levels than survivors." (PMID 40568710, 2025). "The PBMC were separated of twenty patients with sepsis and twenty healthy volunteers, we estimated the mRNA expression level of SRSF7, E2F2, RAB13 and S100A8 in PBMC via RT-qPCR, the mRNA expression level of SRSF7(p<0.0001) was lower in the patients with sepsis than healthy people." (PMID 40909263, 2025). "Similarly, lipid-regulating enzymes ANXA1, S100A8, and FABP5 are co-regulated in a network with ApoE and APP in response to sepsis." (PMID 38653992, 2024). "Circulating S100A8/A9 levels are also increased in hospitalized patients with septic shock, and sepsis survivors show lower serum S100A8/A9 levels than no survivors, which is considered a predictor of mortality in patients with septic shock." (PMID 37569277, 2023). "Notably, pDC B, characterized by high expression of S100A8, S100A9, FCN1 and CD14, was the dominant subtype in the ICU-Sepsis group." (PMID 37781404, 2023). "In agreement with our findings, one Chinese prospective cohort study also performed a comprehensive transcriptome profile analysis and qPCR validation, and suggested S100A8, S100A9, and ANXA3 as key genes differentially expressed between sepsis patients and healthy controls." (PMID 37298316, 2023). "Importantly, levels of MDSCs mediators and the expression of genes with immunosuppressive functions, such as S100A8/A9, S100A12, and ARG1, are highly elevated in patients with sepsis." (PMID 38235139, 2023). "Together, those data showed that S100A8/A9 may function via p38/STAT3/ERK and apoptosis signalling in sepsis-induced pulmonary vascular leakage." (PMID 37978525, 2023). "MMP8 and S100A8 levels in the peripheral blood of sepsis patients were higher in SAE than in non-SAE." (PMID 37901226, 2023). "In this research, using Paquinimod (Paq, also known as ABR25757), an S100A8/A9 specific inhibitor which prevents S100A8/A9 to bind to TLR4, we explored the role of S100A9 in the development of septic AKI in a murine model of cecal ligation and puncture (CLP)-induced sepsis." (PMID 37547329, 2023). "The validation results suggested that S100A8 and SERPINA10 may serve as biomarkers for severe burn patients with sepsis." (PMID 36659877, 2023). "In contrast, in neonates, attempts to establish S100A8/A9 as a clinical biomarker of neonatal sepsis remained without tangible success." (PMID 32425933, 2020). "Whether alarmins, such as S100A8/S100A9, play a role in MDSC expansion and immunosuppression in neonatal sepsis requires further investigation." (PMID 30555806, 2018). "Prestimulation of both murine and human monocytes with S100A8 attenuates IL-6 and TNF-α production in response to LPS and bacteria via downregulation of phosphorylated p38, thus protecting the host against lethal sepsis." (PMID 29942307, 2018).
Sepsis (continued). "We further find that S100A8/A9proteins are released from phagocytes during early, but not late sepsis, and thatcytosolic S100A9 translocates from cytosol to the nucleus of MDSCs." (PMID 29204146, 2017). "This suggests that the single measurement of either S100A8 or S100A9 mRNA levels may be useful for evaluating their response and for use as a potential biomarker in sepsis." (PMID 24956170, 2014). "Our results suggest that S100A8 and S100A9 mRNA levels may be used as surrogate markers of endotoxin tolerance after sepsis." (PMID 24956170, 2014). "Therefore, the goal of our study was to study the regulation of S100A8 and S100A9 mRNA levels in an ex vivo model of endotoxin tolerance, which is known to partially reproduce sepsis-induced innate immune alterations." (PMID 24956170, 2014). "Additionally, surviving patients with sepsis without shock demonstrated significantly elevated serum S100A8/A9 levels (P < 0.0001), whereas those with septic shock showed markedly increased resistin concentrations (P < 0.001)." (PMID 40568710, 2025). "While the AI-driven drug repurposing framework and transcriptomic analyses provide new insights into S100A8/A9 biology in sepsis, they may not fully capture the complexity of in vivo immune responses." (PMID 41303672, 2025). "The sCD13 levels in patients with sepsis also did not correlate with S100A8/A9." (PMID 40168094, 2025). "In this regard, cells from patients with FMF had high levels of S100A8 and S100A9 alarmins but not cells from patients with other inflammatory disorders like sepsis, where these molecules act as ligands for TLR4 and cause strong inflammatory responses within tissues." (PMID 39335710, 2024). "S100A8/A9 (also known as calprotectin) and S100A12 (also known as calgranulin C) are considered biomarkers of potential interest and are proteins members of the calgranulin family which is related to different inflammatory conditions, immune-mediated diseases, and sepsis." (PMID 37627347, 2023). "Additionally, surviving patients had significantly lower S100a8/a9 levels compared with non-survivors in sepsis." (PMID 37396347, 2023). "Pharmacological blockade of S100A8/A9 with ABR-238901 has potent anti-inflammatory effects, mitigates myocardial dysfunction and might represent a novel therapeutic strategy for patients with severe sepsis." (PMID 37773186, 2023). "Our data showed that both S100A8 and S100A9 expression were highly upregulated in the liver tissues of CLP-treated mice, suggesting that elevated S100A8/A9 may be involved in sepsis-induced acute liver injury." (PMID 36768433, 2023). "In our sepsis patient survival analysis, G-CSF and neutrophil lifespan shortening activity correlated with mortality whereas plasma histones or DNA did not, despite their correlation with plasma S100A8/9 concentrations." (PMID 35945238, 2022). "Interestingly, S100A8/S100A9 have been described to specifically interact with the TLR4-CD14-MD2 complex, thus representing inflammatory components that amplify phagocyte activation during the sepsis upstream of TNF-α-dependent effects." (PMID 35741108, 2022). "S100A8 and S100A9 have implication on “inflammatory response”, “macrophage activation” and “neutrophil activation” These molecules may serve as signature of sepsis." (PMID 32922168, 2020). "In addition, we detected S100A8 proteinmainly in the cytosol in early and late sepsisGr1+CD11b+ cells, but its levels weremarkedly reduced in late sepsis cells (data not shown), likely due to lack of S100A9in the cytosol." (PMID 29204146, 2017). "Due to the embryonic lethality observed in S100A8-deficient mice and the lack of S100A8/A9 protein expression in S100A9-deficient mice, S100A9 knockout (KO) mice were used in this study to explore the role of S100A8/A9 in sepsis-induced pulmonary vascular hyperpermeability." (PMID 37978525, 2023).